ENSG00000252408
Gene: Small nucleolar RNA gene on chromosome 19 (3,521,248 to 3,521,320, reverse strand). Ensembl gene ENSG00000252408.
Homologues: Orthologues: mouse Gm22980 (71% identical), rat Snord38b (71% identical). Paralogues in human: SNORD38B (75% identical), SNORD38C (75% identical), SNORD38D (75% identical), SNORD38A (63% identical).